SC5D (sterol-C5-desaturase)
Description:
Catalyzes the penultimate step of the biosynthesis of cholesterol, the dehydrogenation of lathosterol into 7-dehydrocholesterol (7-DHC). Cholesterol is the major sterol component in mammalian membranes and a precursor for bile acid and steroid hormone synthesis. In addition to its essential role in cholesterol biosynthesis, it also indirectly regulates ferroptosis through the production of 7-DHC. By diverting the spread of damage caused by peroxyl radicals from the phospholipid components to its sterol nucleus, 7-DHC prevents this form of cell death.
Synonyms: SC5DL; ERG3; S5DES
Tractability: Antibody: UniProt predicts a signal peptide or a membrane-spanning region; the Human Protein Atlas places it where antibodies can reach. PROTAC: ubiquitination databases record sites on it; its protein half-life has been measured.
Target class: Enzyme; Oxidoreductase
Gene: Protein-coding gene on chromosome 11 (121,292,681 to 121,313,410, forward strand). Ensembl gene ENSG00000109929.
Subcellular location: Endoplasmic reticulum membrane
Subcellular location (Human Protein Atlas): Endoplasmic reticulum; Nucleoplasm; Cytosol; Plasma membrane
Pathways (Reactome):
Metabolism: Activation of gene expression by SREBF (SREBP); Cholesterol biosynthesis from zymosterol (modified Kandutsch-Russell pathway); Cholesterol biosynthesis via desmosterol (Bloch pathway)
Gene Ontology:
Molecular function: C-5 sterol desaturase activity; delta7-sterol 5(6)-desaturase activity; iron ion binding; sterol desaturase activity
Biological process: cholesterol biosynthetic process; negative regulation of ferroptosis; lipid biosynthetic process
Cellular component: endoplasmic reticulum membrane
Genetic constraint (gnomAD): Loss-of-function variants: 17 observed, 19.57 expected, observed/expected ratio (o/e) 0.87, 90% interval 0.59 to 1.3. The upper end of that interval is the gene's LOEUF score, 1.3, which puts it in group 5 of 6, group 1 being the genes least tolerant of losing a copy. Missense variants: 259 observed, 316.38 expected, observed/expected ratio (o/e) 0.82, 90% interval 0.74 to 0.91. Synonymous variants: 94 observed, 111.83 expected, observed/expected ratio (o/e) 0.84, 90% interval 0.71 to 1.
Homologues: Orthologues: chimpanzee SC5D (98% identical), macaque SC5D (96% identical), dog SC5D (87% identical), rabbit SC5D (86% identical), mouse Sc5d (84% identical), pig SC5D (83% identical), rat Sc5d (82% identical), guinea pig SC5D (81% identical), tropical clawed frog sc5d (66% identical), zebrafish sc5d (66% identical). Paralogues in human: MSMO1 (22% identical), FAXDC2 (18% identical), CH25H (17% identical).
Diseases named in the same sentence as SC5D in open-access papers:
SC5D is named in the same sentence as 22 diseases in open-access papers, as found by Europe PMC text mining. Sharing a sentence is not in itself a finding about the gene and the disease. The quoted sentences say what the papers report.
lathosterolosis (10 papers, 2011 to 2024). Lathosterolosis is an extremely rare inborn error of sterol biosynthesis characterized by facial dysmorphism, congenital anomalies (including limb and kidney anomalies), failure to thrive, developmental delay and liver disease. "SC5D deficiency can result in lathosterolosis, a clinical syndrome with a complex phenotype involving multiple congenital anomalies, intellectual disabilities, and liver failure." (PMID 38672427, 2024). "Mutations in Dhcr7 and Sc5d, which encode enzymes that catalyze the terminal steps in cholesterol biosynthesis, impair HH signaling in target cells and cause the congenital malformation syndromes Smith-Lemli-Opitz and lathosterolosis, respectively." (PMID 31657721, 2019). "For example, pathogenic variants in the lathosterol oxidase gene, SC5D, cause lathosterolosis, which is associated with microcephaly, intellectual disability, micrognathia, high arched palate, and cataract." (PMID 37774976, 2023). "Additionally, lathosterolosis and microcephaly, congenital cataract, and psoriasiform dermatitis (MCCPD), caused by deficiency in either sterol-C5-desaturase (SC5D) or methylsterol monoxygenase 1 (MSMO1), is known to display cataracts as one of the clinical features." (PMID 34021134, 2021). "Dysfunction of SC5D and DHCR7 leads to lathosterolosis and desmosterolosis, respectively." (PMID 38438535, 2024).
atherosclerosis (1 paper, 2022). A disease characterized by the build-up of fatty material and calcium deposition in the arterial wall resulting in partial or complete occlusion of the arterial lumen. "Gene regulatory network analysis identified specific liver regulators related to lipid metabolism (SC5D, LCAT and HMGCR), inflammation (IL1A) and fibrosis (PDGF, COL3A1), linked to a set of aorta target genes related to vascular inflammation (TNFA) and atherosclerosis signaling (CCL2 and FDFT1)." (PMID 35897797, 2022). "Using this method, we identified several hepatic regulators related to lipid metabolism (SC5D, LCAT and HMGCR), inflammation (IL1A) and fibrosis (PDGF and COL3A1) that were linked to a set of aorta target genes related to vascular inflammation (TNFA) and atherosclerosis signaling (CCL2 and FDFT1)." (PMID 35897797, 2022).
COVID-19 (1 paper, 2022). A disease caused by infection with severe acute respiratory syndrome coronavirus 2. "Among them, six (ADK, DHFR, METAP2, PIN4, SC5D, and TMEM263) had matching risk factor genes showing consistent patterns, i.e., transcriptional downregulations increased the COVID-19 mortality risk." (PMID 35547187, 2022).
developmental delay (1 paper, 2024). "Sc5d KO mice are smaller than littermate controls and present developmental delay and bent shorter limbs." (PMID 38438535, 2024).
Smith-Lemli-Opitz syndrome (1 paper, 2021). Smith-Lemli-Opitz syndrome (SLOS) is characterized by multiple congenital anomalies, intellectual deficit, and behavioral problems. "Examples of such congenital disorders and the affected enzymes include Smith-Lemli-Opitz syndrome (SLOS; DHCR7, OMIM# 270400), desmosterolosis (DHCR24, OMIM# 602398), lathosterolosis (sterol-C5-desaturase, OMIM# 607330), and mevalonate kinase (MVK, OMIM# 251170) deficiency." (PMID 33662384, 2021).
cancer (5 papers, 2019 to 2026). A tumor composed of atypical neoplastic, often pleomorphic cells that invade other tissues. "It has been postulated that a reduction in SC5D activity in cancer could promote the prenylation of Ras, Rac or RhoC, impacting cancer progression." (PMID 41596244, 2026).
tumor (1 paper, 2018). "The average tumor expression signals of ACSS3, DHCR14, and SC5D are higher than the expression in normal parental tissues." (PMID 29493120, 2018).
SC5D also shares sentences with these, for which no sentence is quoted: infection (3 papers); Intellectual disability (3); microcephaly (2); amyotrophic lateral sclerosis (1); cataract (1); colon cancer (1); congenital cataract (1); congenital malformation syndromes (1); desmosterolosis (1); frontotemporal dementia (1); gastric cancer (1); Listeria infection (1); liver failure (1); neurological disorders (1); Psoriasiform dermatitis (1).